RNU6-1067P (RNA, U6 small nuclear 1067, pseudogene)
Gene: Small nuclear RNA gene on chromosome 10 (28,667,919 to 28,668,025, forward strand). Ensembl gene ENSG00000207483.
Homologues: Orthologues: chimpanzee U6 (100% identical), mouse Gm23649 (91% identical), macaque U6 (89% identical), rat LOC120099424 (75% identical). Paralogues in human: RNU6-16P (93% identical), RNU6-1 (93% identical), RNU6-1145P (93% identical), RNU6-2 (93% identical), RNU6-35P (93% identical), RNU6-39P (93% identical), RNU6-3P (93% identical), RNU6-4P (93% identical), RNU6-5P (93% identical), RNU6-6P (93% identical), RNU6-9 (93% identical), RNU6-12P (92% identical), and 1284 more.